BRCA1 (BRCA1 DNA repair associated)
Diseases named in the same sentence as BRCA1 in open-access papers (continued):
Sharing a sentence is not in itself a finding about the gene and the disease.
breast cancer (continued). "Moreover, the expression pattern of PARP1, γH2AX, and BRCA1/2 predicted shorter survival of various human malignant tumors including breast carcinoma and soft tissue sarcomas." (PMID 29784019, 2018). "Increased risk of breast cancer with smoking has also been seen in some, but not all (see review and a large meta-analysis), studies of BRCA1/2 carriers (or by proxy, women with three or more first-degree relatives with breast or ovarian cancer)." (PMID 29162146, 2017). "Of the genetic factors, the inherited germline mutations in two genes: BRCA1 and BRCA2, are the well-established risk factors of breast cancer, explaining approximately two percent of breast cancer cases (up to 7 percent among Polish women diagnosed before age 50)." (PMID 28594926, 2017). "BRCA1/2 mutation status was not available in our study population, and family history of breast cancer is missing for the majority of participants (64%)." (PMID 28173834, 2017). "However, little is known about how women identified as carrying a BRCA1/BRCA2 mutation after an ovarian cancer diagnosis adjust to and view their breast cancer risk." (PMID 28780755, 2017). "Men in the 3rd and 4th quartiles were at significantly increased risk of breast cancer compared with men in the bottom quartile of the PRS, but the numbers of carriers in individual quartiles in the BRCA1 only analyses were too small to draw definitive conclusions." (PMID 28448241, 2017). "However, BRCA1 and BRCA2 mutations are very rare and only accounts for around 5% of all breast cancers." (PMID 28607444, 2017). "Unaffected women undergoing mutation testing for BRCA1/2 should be advised that there is limited reassurance from a negative test result if their close relative had a HER2+ breast cancer." (PMID 27796713, 2017). "Genetically, breast cancer has autosomal dominant inheritance, predominantly for BRCA1/2 genes." (PMID 28962650, 2017). "A previous study links POI to other breast cancer genes such as BRCA1." (PMID 29231814, 2017). "The results from the Breast Cancer Linkage Consortium showed a relative risk (RR) of 4.65 of PCa among male BRCA2 mutation carriers with a RR of 7.33 below the age of 65 years and of 1.07 in BRCA1 carriers." (PMID 29262604, 2017). "Studies and meta-analyses of breast cancer cases have shown that BRCA1 with or without BRCA2 mutations is linked to a poor outcome." (PMID 29152070, 2017). "AR has been shown to be expressed in 80% of BRCA2 mutated breast cancer as opposed to only 30% of BRCA1 mutated breast cancer." (PMID 28863181, 2017). "In the end, we may be observing, how an opposite action between a tumour suppressor gene (BRCA1) and an oncogene (E2F) takes place, during the development of breast cancer." (PMID 28496157, 2017). "Since FOXP3 is a transcriptional repressor of BRCA1, a transcriptional repressor of miR-155, BRCA1 may be a mediator for transcriptional regulation of miR-155 by FOXP3 in human breast cancer cells." (PMID 28562349, 2017). "Next, we analyzed whether knockdown of BRCA1 could induce β-hCG in BRCA1 wild-type breast cancer cells." (PMID 28869585, 2017). "There is currently no consensus on eligibility criteria for WES in BRCA1/2 mutation-negative familial breast cancer patients." (PMID 28241424, 2017).
breast cancer (continued). "The preeminent knowledge accessible to date is based on a joint investigation of 22 researches, 11 which established that the prevalence of breast cancer is 65% at 70 years of age in women who acquired a BRCA1 gene and 45% in those women who are carriers of BRCA2 genes." (PMID 28969709, 2017). "Previous studies have detected a shift in BRCA1 from nucleus to cytoplasm in breast cancer." (PMID 28863181, 2017). "Thus, for future studies, we will examine the expression of Rak in breast cancer cell lines and tissues with WT and mutant BRCA1 and the regulation of mutant BRCA1 stability by Rak." (PMID 29156836, 2017). "BRCA1/2 mutation prevalence in familial breast cancer cases was 15.9%, which was significantly higher in non-familial breast cancer cases (6.0%, P = 0.004)." (PMID 28205045, 2017). "Penetrance analyses of the complete set of pedigrees using Mendel resulted in a HR of breast cancer by age 70 years equal to 2.81 (95% CI 1.47 to 5.35) for carriers of founder BRCA1 mutations compared to non-carriers." (PMID 28680148, 2017). "Therefore, we combined these 6 patients with the 12 BRCA1- and 1 BRCA2-mutated hereditary breast cancer patients into one group (donated as “BRCA”)." (PMID 29146938, 2017). "MDA-MB-436 BRCA1-/- breast cancer cells were depleted of EEPD1 and/or RAD52 using siRNA." (PMID 29145865, 2017). "Within the breast cancer cell lines we screened lacking BRCA1/2 mutations, the PARPi sensitivity signature predicted to five to be sensitive (HCC-1806, CAMA1, MCF7, MDA-MB-231, and BT-549)." (PMID 28649435, 2017). "The identification of BRCA1/2 mutation has a beneficial impact on the management and access to specific treatments (i.e., PARP inhibitors) for patients, and for counseling of relatives at risk, in order to reduce breast cancer mortality." (PMID 28577564, 2017). "The incidence of breast cancer is high in some families whose BRCA1 or BRCA 2 is mutant." (PMID 28881705, 2017). "Tung and co-workers tested a 25-gene-panel on 1781 breast cancer patients who were referred for BRCA1/2 gene testing at Myriad Genetics and found that 9.3% of the patients harboured a mutation in the BRCA1/2 genes, but 4.2% of the patients carried a mutation in 14 additional genes." (PMID 28146134, 2017). "Considered tumor suppressor genes, the inactivation of BRCA1 and BRCA2 after loss of heterozygosity confer a risk of 56 to 87% of development of breast cancer in women and somatic mutations of BRCA2 are associated with aggressive metastasis in lymph nodes in humans." (PMID 28945747, 2017). "In this way, risk-reducing surgery was raised as having been proven to reduce breast cancer risk in BRCA1/BRCA2 carriers, but also as something not usually considered when the focus is on ovarian cancer treatment." (PMID 28780755, 2017). "The detection rate of MGPT was 18.1% for patients tested for variants in 16 breast cancer susceptibility genes and with no prior BRCA1/2 testing." (PMID 28008555, 2017). "So whereas a higher median of SNV numbers has indeed been observed in BRCA1/2-defective breast cancer samples, the mutation rates are not known." (PMID 27452521, 2017). "Hope and optimism have also been found as facilitating adaptation to an increased familial breast cancer risk, when this has been studied in women from high-risk families with and without a BRCA1/BRCA2 mutation." (PMID 28780755, 2017). "Because deleterious germline mutations in BRCA1 and BRCA2 have been significantly associated with breast cancer, we assessed whether germline mutations in these two genes were present in our cohort." (PMID 28977883, 2017). "This study was conducted in order to characterize women with personal and family history of breast cancer (with and without germline mutation in BRCA1) regarding their clinical and molecular characteristics (mutation and methylation in BRCA1)." (PMID 27926510, 2017).
breast cancer (continued). "Similar to the brc-1 ortholog BRCA1, HORMAD1, SETD1A, KMT2C, and KM2D/MML4 have all been linked to breast cancer, suggesting that these genetic interactions may be conserved in human cells." (PMID 28506208, 2017). "This analysis confirms that the HISPANEL is not reliable for screening BRCA1/2 mutations in our breast cancer patients." (PMID 29088781, 2017). "60% to 90% of BRCA1-associtaed breast cancers are HR negative, and these patients have a much higher risk for developing a second breast cancer." (PMID 28467490, 2017). "In this study, two BRCA1/2 mutation-negative breast cancer patients were selected from the same family for WES, followed by extended mutation screening in 164 unrelated cases stratified according to ER status." (PMID 28241424, 2017). "PALB2 exons were amplified from 460 BRCA1/2-mutation negative women with familial breast and/or ovarian cancer and early-onset breast cancer using AmpliSeq technology and sequenced on an Ion Torrent PGM sequencer." (PMID 28279176, 2017). "The BRCA1 and BRCA2 genes were first reported as breast cancer predisposing genes." (PMID 29299148, 2017). "Our results demonstrate that approximately 4.7% of BRCA1/2 negative familial breast cancer women have mutations in genes statistically associated with breast cancer." (PMID 28649662, 2017). "Further, β-hCG promotes migration and invasion predominantly in BRCA1 mutant breast cancer cells." (PMID 28869585, 2017). "So far, no data on the prognostic significance of VDR in BRCA1 mutated breast cancer have been published." (PMID 28427429, 2017). "In another study, women lacking functional BRCA1/BRCA2 at increased breast cancer risk also show greater risk for heart disease and metabolic diseases." (PMID 28698603, 2017). "However, in this study, we further demonstrated that, more importantly, CTSO can also directly regulate BRCA1 protein turnover in breast cancer cells." (PMID 28968398, 2017). "The overall mutation-positive rate for breast cancer susceptibility genes for patients with no prior BRCA1/2 testing reported was 18.1% (N = 64/354), with 1.1% (n = 4) of patients carrying pathogenic variants in two different breast cancer genes." (PMID 28008555, 2017). "We have reported that CpG methylation of the ER gene is more extensive in ER-negative BRCA1-linked breast cancers compared with ER-negative breast cancers not linked to germline mutations in BRCA1." (PMID 28270739, 2017). "In summary, NHERF1 expression could be considered a new potential biomarker in combination with PARP1 and BRCA1 expression to stratify breast cancer patients." (PMID 29029467, 2017). "Even though all females who acquire a BRCA1 or BRCA2 variant do not essentially cause breast cancer, it is uncertain what other determinants such as genetic or environmental persuade the risk of breast." (PMID 28969709, 2017). "As PALB2 links BRCA1 and BRCA2 and mutations in this gene is associated to susceptibility to breast cancer, it became a natural question whether PALB2 mutations could also lead to OC." (PMID 28858227, 2017). "Female relatives of carriers of BRCA1/2 founder mutations showed a 5.90 times higher risk of breast cancer, when the woman herself carried a BRCA1 mutation compared to a non-carrier (95% CI 2.01–17.3)." (PMID 28680148, 2017). "Interestingly, PARP1 activity is indispensable for normal proliferation of mammary tumor cells, in which a gene encoding an HRR factor BRCA1 is mutated, because PARP1 inhibition blocks alternative DNA repair pathways including NHEJ5." (PMID 29158484, 2017). "Third; BRCA1/2 mutations were associated with breast cancer, however in this retrospective study BRCA 1/2 status was not available." (PMID 27895314, 2017).
breast cancer (continued). "How does oxidative stress effect wild type BRCA1 in breast cancer cells?" (PMID 28262780, 2017). "Decreased BRCA1 expression has been shown to be present in 30–40% of sporadic breast cancers." (PMID 28968398, 2017). "Consanguinity can lower breast cancer risk (BCR) as homozygosis of mutated DNA-repair genes like BRCA1 and BRCA2, being incompatible with life, are not transmitted to the next generation." (PMID 29157216, 2017). "Our data indicated that BRCA1 expression and subcellular localization might stand as an independent prognostic factor in breast cancer which is supported by similar findings from previous studies." (PMID 28863181, 2017). "Conversely patients with a VUS on BRCA1 and those harboring WT BRCA1 had a similar proportion of triple negative tumors (31.8% and 32.6% respectively), a percentage slightly higher than that observed in sporadic cases of breast cancer." (PMID 27926510, 2017). "Worse survival outcomes have been reported in BRCA2-mutated breast cancer (but not BRCA1) compared to sporadic cancers, independent of treatment, in some population-based studies, which seems to be due to adverse tumour characteristics." (PMID 29069866, 2017). "A third study found a younger age of menopause in BRCA1 mutation carriers with and without breast cancer." (PMID 28831696, 2017). "Standard treatment of BRCA1-associated breast cancer does not differ from other types of breast cancer, although targeted approaches are emerging." (PMID 28977823, 2017). "Differences in gene expression levels between cancer and non-cancer samples, as well as between the HN and CN, were consistent with the already known hallmarks of cancer, in particular for breast cancer, such as the activity via estrogen or BRCA1 signalling pathways." (PMID 28496157, 2017). "In this study, a pathology-supported genetic testing (PSGT) approach was used to select two BRCA1/2 mutation-negative breast cancer patients from the same family for WES." (PMID 28241424, 2017). "Although some known breast cancer susceptibility loci are also associated with mammographic density, mutations in highly penetrant breast cancer genes; BRCA1 and BRCA 2 genes have not been found to be associated with mammographic density." (PMID 29088745, 2017). "Our method identified not only many known cancer genes such as CCND1, MYC, ERBB2, RB1 and BRCA1 in breast cancer but also many novel protein‐coding genes as well as non‐coding RNAs that may contribute to carcinogenesis." (PMID 28719033, 2017). "We here examined whether Nestin, by protein and mRNA levels, could be a predictor of BRCA1 related breast cancer, a basal-like phenotype, and aggressive tumours." (PMID 28439082, 2017). "Breast cancer patients with family history of breast and ovarian cancer showed the highest prevalence of BRCA1/2 mutations (67%), and triple-negative breast cancer (TNBC) patients showed high BRCA1 mutation prevalence (25%)." (PMID 28205045, 2017). "When XRCC4 or LIG4 were depleted in the EEPD1/RAD52 co-depleted BRCA1-deficient breast cancer cells, no significant reduction in cell survival was observed." (PMID 29145865, 2017). "TNBCs clinical and pathologic features overlap with hereditary BRCA1 related breast cancers." (PMID 28052035, 2017). "Despite the family history of breast cancer, no known pathogenic BRCA1 or BRCA2 germline variants were identified." (PMID 28487881, 2017). "BRCA1 mutated breast cancers are commonly diagnosed as negative for classical hormone receptors i.e. estrogen receptor, progesterone receptor and/or Her2." (PMID 28427429, 2017). "To date, the application of PARP inhibitors to TNBC has mainly been based on the morphologic-molecular similarities with BRCA1-mutated breast cancers and on the results from clinical studies, but not on PARP-related pathways or on the status of PARP proteins." (PMID 29029467, 2017).
breast cancer (continued). "In addition to BRCA1 or BRCA2 gene mutations, there are other geneticsyndromes that increase the risk for breast cancer." (PMID 28894332, 2017). "Furthermore, ternary complex formation and PARP1 redistribution protect cells from DNA damage by promoting DNA repair, and support growth of BRCA1-null mammary tumors, which are sensitive to PARP inhibitors." (PMID 29158484, 2017). "This type of unselected genetic testing in newly diagnosed women with epithelial ovarian cancer is leading to more families without a strong history of breast cancer being found with germline BRCA1/BRCA2 mutations." (PMID 28780755, 2017). "A negative BRCA1/2 mutation test only drops absolute breast cancer risk by 1.7% if mother was Her2+ but by nearly 6% when triple negative." (PMID 27796713, 2017). "In conclusion, our study identifies BRCA1 as a novel potential biomarker in breast cancer." (PMID 28706506, 2017). "Although the majority of breast cancers in BRCA1 mutation carriers are ER negative, the proportion of ER-negative breast tumors decreases with increasing age at diagnosis." (PMID 28376175, 2017). "Although mutations in the BRCA1 are rare in non-familial mammary carcinomas, it is common to have loss of expression in 40 to 50% of sporadic mammary tumors, possibly through epigenetic alterations, specifically promoter hypermethylation." (PMID 28945747, 2017). "PI3K and Parp-1 inhibitors has proven effective in treating Brca1-related breast cancer in vivo." (PMID 29254138, 2017). "Rare mutations conferring high risk of breast cancer, for example in BRCA1/2 genes are not included in this score." (PMID 28830573, 2017). "We have investigated the metabolic profiles of human breast cancer (BC) cell lines carrying BRCA1 pathogenic mutations by non-targeted liquid chromatography coupled to mass spectrometry technology." (PMID 29259228, 2017). "In the present study, we analyzed by a multiplex ELISA plasma-blood assay, the expression of leptin, adiponectin and ghrelin in breast cancer patients and their healthy relatives belonging to families with Hereditary Breast Cancer Syndrome and with known BRCA1/2 gene molecular status." (PMID 29254161, 2017). "Furthermore, the HSF1-mediated DDR mechanisms protect tumor cells from DNA damage, especially supporting growth of BRCA1-null mammary tumors, which are sensitive to PARP inhibitors." (PMID 29158484, 2017). "The correlation between loss of BRCA1 and the ER-negative phenotype extends to sporadic (i.e. non-inherited) breast cancers as well." (PMID 28270739, 2017). "Tamoxifen has been associated with an approximately 50–70% reduction in the risk of contralateral breast cancer in BRCA1/2 carriers, but prospective studies of BRCA1 carriers have not been done." (PMID 28624978, 2017). "To determine whether acetaldehyde toxicity to olaparib‐resistant cells can be recapitulated in vivo, we established tumor allografts from Brca1+/+, Brca1−/−, and PARP inhibitor‐resistant Brca1−/−, 53BP1‐deficient mouse mammary tumor cells." (PMID 28729482, 2017). "Likewise, viral vectors have been used to administer a breast cancer gene BRCA1 and retinoblastoma gene into ovarian cancer and bladder, correspondingly." (PMID 28969709, 2017). "In addition to clinical pathologic features, BRCA1 and BRCA2 are functional proteins associated with breast cancer." (PMID 28938549, 2017). "To determine how generalizable this phenomenon might be, we also measured the level of BRCA1 protein in triple negative MDA-MB-231 breast cancer cells." (PMID 28968398, 2017). "Germline pathogenic variants in the tumor suppressor genes BRCA1 (MIM# 113705) and BRCA2 (MIM# 600185) are associated with increased risk of breast and ovarian cancer, and account for about 16% of the familial risk for breast cancer." (PMID 28339459, 2017). "BRCA1 physically binds to BARD1, another protein that was linked to breast cancer susceptibility." (PMID 28506208, 2017).